CD4 (CD4 molecule)
Diseases named in the same sentence as CD4 in open-access papers (continued):
Sharing a sentence is not in itself a finding about the gene and the disease.
cervical carcinoma (continued). "The levels of IL-1beta, IL-2, TNF-alpha, and IL-10 were negatively correlated with the percentages of CD4+NKG2D+ T cells in patients with cervical carcinoma." (PMID 26486970, 2015). "We found an increased percentage of CD4+NKG2D+ T cells in patients with cervical cancer when compared with controls." (PMID 26486970, 2015). "Once again, control and cervical cancer groups were divided into the three different ranges of CD4+NKG2D+ T cells (0–2, 2–4, and >4 %)." (PMID 26486970, 2015). "Particularly, patients with advanced cervical cancer have exhibited a markedly reduced proportion of CD28+ cells within both CD4+ and CD8+ T cell subpopulations." (PMID 26486970, 2015). "Cervical cancer cells secrete high levels of TGF-β that inhibit tumor infiltration by apoptosing CD4 lymphocytes evading host immune system." (PMID 25786122, 2015). "Women with low CD4 cell counts have a higher HPV viral load, and a greater risk of persistent HPV infection and cervical cancer." (PMID 24484380, 2014). "Higher frequencies of HPV-specific Treg are found in the stroma, intraepithelial tissues and tumor draining lymph nodes of cervical cancer patients where they suppress alloreactive CD4+ responder T cells." (PMID 24639678, 2014). "Most of the patients (77%) diagnosed with cervical cancer had a CD4+ T-cell count >200 cells/mm3 and almost half of them (44%) had a nadir CD4+ count >200 cell/mm3." (PMID 24760049, 2014). "On average, HIV positive women with early cervical cancer disease had significantly more CD4+ cells than those with advanced disease (385.8 ± 170.4 95% CI 354.8-516.7 and 266.2 ± 87.5, 95% CI 213.3-319.0 respectively p = 0.042)." (PMID 22862747, 2012). "Most of the HIV positive patients (68.2%) had a CD4+ count of less than 350cells/μl indicating the need for HIV screening of all cervical cancer patients so that appropriate treatment is initiated concurrent with cervical cancer management." (PMID 22862747, 2012). "CD4+ count of 350/μL and less was seen more often among women with advanced cervical cancer than those who had more counts although the difference was not statistically significant." (PMID 22862747, 2012). "Results from this study suggest that HIV seropositivity is associated with cervical cancer cell differentiation and that HIV co-infected women present with relatively low CD4+ count." (PMID 22862747, 2012). "Our data indicate that TCR transfer is feasible as an alternative strategy to generate human HPV16 specific CD4+ T helper cells for the treatment of patients suffering from cervical cancer and other HPV16 induced malignancies." (PMID 21892941, 2011). "Results indicated that expression rates of CD8 and CD4 molecules in cervical cancer group were significantly lower than in CIN, chronic cervicitis and peri-cancer group (P < 0.01)." (PMID 29147220, 2011). "The percentage of positive tissue staining of HLA-I, CD8 and CD4 were significantly lower in tissues of cervical cancer when compared with other tissues (P < 0.01)." (PMID 29147220, 2011). "The expression of CD8+ T cells and CD4+ T cells were also statistically low in the cervical cancer group than in other groups." (PMID 29147220, 2011). "We present here results from a study of invasive cervical carcinoma (ICC) in relation to HPV status, HIV status and CD4 count in Uganda, where the estimated world-standardised incidence rates of cervical cancer is rising and is now 52.4 per 100 000 women." (PMID 21702999, 2011). "No statistical different positive tissue staining of CD8 and CD4 was found in cervical cancer group when correlated with clinical stages, cell differentiation, and lymph node metastasis." (PMID 29147220, 2011). "Although HIV-positive women with cervical cancer had lower median CD4 counts than did HIV-positive controls, the difference was not statistically significant (376 cells/μl vs. 572 cells/μl: p = 0.6)." (PMID 20716343, 2010).
cervical carcinoma (continued). "It was shown that cervical cancer had a moderate amount of neoantigens and TMB among all cancers, while some cervical cancers contained tumor‐infiltrating immune cells like activated memory CD4+ T‐cells, which could further modulate the tumor microenvironment." (PMID 40908776, 2025). "Cervical cancer patients display a Th2-skewed CD4+ response and reduced IFN-γ levels." (PMID 40264780, 2025). "We could observe that in cervical cancer patients, the CS High group had a higher proportion of B cell, CD4+ T cell, CD8+ T cell, Neutrophil, and DC." (PMID 40936719, 2025). "Our findings highlight the role of CD4 counts, as a measure of HIV control and immunity, in controlling hrHPV infection, which could potentially impact cervical cancer control among this high-risk population." (PMID 40991629, 2025). "Our findings highlight the role of CD4 counts, as a measure of HIV control and immunity, on controlling hrHPV infection, which could potentially impact cervical cancer risk." (PMID 40991629, 2025). "Although there is a growing body of literature describing changes in the immunologic profiles of patients receiving treatment for cervical cancer, most are limited to broad characterizations of lymphocyte fluctuations and lack detail about behavior of specific subsets of CD4 and CD8 cells." (PMID 40099965, 2025). "IL‐17 expression was not solely found in T cells in cervical cancers; however, our analysis revealed that numbers of IL‐17‐expressing CD4 negative cells are not linked to SDHD expression in cervical cancers." (PMID 37899663, 2024). "Interestingly, among the immune cells that infiltrated cervical cancer, the increased proportion of activated memory CD4+ T cells has a good survival prognosis, and vice versa." (PMID 38169557, 2024). "Secondly, the association between lower CD4+ cell counts, and multiple HR-HPV infections reinforces the importance of effective ART adherence to maintain immune function and reduce the burden of cervical cancer." (PMID 39070626, 2024). "Additionally, the combination of NK cells, activated CD4+ T cells and activated mast cells can improve the ability to predict the overall survival of patients with cervical cancer." (PMID 38169557, 2024). "For many years, HIV-infected women’s risk for cervical cancer remained high and stable, and incidence did not decrease with improving CD4 cell counts." (PMID 38216912, 2024). "NAT10/ac4C/FOXP1 axis was reported to facilitate immunosuppression and overexpression of FOXP1 was found to be positively related to the infiltration of activated CD4+ T cells and Tregs in cervical cancer, which supports our hypothesis." (PMID 38652109, 2024). "The enriched genes included CD4 in cervical cancer, VPS52, NUP62, CRYGD, IL34, GATA3 in prostate cancer and F11, TXNIP, KIT, ASGR2, SERPINF1 in liver cancer, which also provide insight into the molecular mechanisms underlying cancer progression and the potential impact on patient survival." (PMID 37393582, 2023). "There has been many findings including from a recent systematic review and meta-analysis concerning the role of ART, CD4 count and viral load levels and HPV infection and cervical cancer risk which suggests that sustained viral suppression from ART can have a positive impact on CC prevention." (PMID 37237313, 2023). "It was observed that an increased number of circulating CD4+ NKG2D+ T-cells and a low expression of CD28 costimulatory receptors in cervical cancer patients is linked to a diminished frequency of cytotoxic markers and reduced production of pro-inflammatory cytokines." (PMID 36831674, 2023). "In addition to CD8 positive cells, cervical cancer TILs include CD4 positive cells, αβ T cells, γδ T cells, B cells, natural killer cells, and regulatory T cells (Tregs)." (PMID 36831552, 2023). "In addition, NKG2D+ CD4+ T cells were found in cervical carcinoma while missing on CD4+ T cells in the physiological state." (PMID 36532071, 2022).
cervical carcinoma (continued). "Moreover, rapid tumor growth and lymph node metastasis are closely related to the reversion of the CD8 +/CD4 + ratio in patients with cervical cancer." (PMID 36185274, 2022). "However, our study only compared the bulk CD8+/CD4+ TILs in cervical cancer and is unable to distinguish Fr-III from bulk CD4+ TILs." (PMID 34150643, 2021). "Therefore, the proportion of CD4+, CD8+, and CD4+/CD8+ cells can directly reflect the cellular immune function of patients with cervical cancer." (PMID 34956380, 2021). "In this context, it will be important to clarify whether early ART treatment initiation, when CD4 T-cell counts are still high, may counteract HIV-induced T-cell dysfunction, reduce risk for HPV virus persistence thereby reducing the risk of cervical cancer." (PMID 34759925, 2021). "However, a significant higher count of B cell, CD8 positive T cells, resting CD4 positive T memory cells, regulatory T cells, gamma delta T cells, and resting NK cells were presented in cervical cancer samples with high CDHR5 expression." (PMID 35071000, 2021). "Similarly, another report indicated a significantly higher expression ratio of CD4/CD25 Tregs in TILs than in PBLs of human cervical cancer." (PMID 34553029, 2021). "It was known that the activated memory CD4 T cells could secret interleukin (IL) 17, a proinflammatory cytokine that promotes the proliferation and growth of cervical cancer." (PMID 34030645, 2021). "Moreover, our study also demonstrated that CD8+/CD4+ TIL ratio and HPV infection status are risk factors for early relapse and mortality in cervical cancer patients." (PMID 34150643, 2021). "This role is highlighted by evidence that cervical cancer is associated with a lower CD4 cell count and no ART among women living with HIV." (PMID 33212031, 2021). "Previous studies of patients with cervical cancer have described alterations in T cell and NK cell populations, suppression of NK cell activity by CD4+ regulatory T cells, and reduced numbers of CD4+ T cells and NK cells in the neoplastic cervix." (PMID 32309426, 2020). "By investigating a correlation between the risk score and immune cells in cervical cancer patients, we found that patients with low risk scores had high infiltration levels of B cells, CD8+ T cells, CD4+ T cells, macrophages, neutrophils, and dendritic cells in the immune microenvironment." (PMID 33173530, 2020). "It has been shown that TIM-3 expression on CD4+ TILs may promote potential metastatic characteristics in cervical cancer TME." (PMID 32041340, 2020). "Although NAC for cervical cancer appears not to suppress lymphocyte numbers, lower levels of CD4+ T cells, CD8+ T cells, and NK cells are associated with a poorer response to chemotherapy." (PMID 32309426, 2020). "In a clinical study, the 5-year survival rate of cervical cancer patients with high CD4+/ CD8+ ratio was higher than that of patients with low CD4+/ CD8+ ratio, increasing the CD4+/ CD8+ ratio can slow the progression of cervical cancer and improve its prognosis." (PMID 32847505, 2020). "T cells, such as CD4+ and T-regs, infiltrate the tissue in cervical cancer." (PMID 31284453, 2019). "And the differences in CD4+ T cells infiltration could be associated with the differences in survival of HPV-positive OPSCC and cervical cancer patients." (PMID 31001266, 2019). "Some studies have demonstrated that low CD4 counts do not necessarily amount to increased risk of cervical cancer and other HPV-related cancers." (PMID 31073325, 2019). "CD4+CD25+Foxp3+ Tregs play an important role in the pathogenesis of cervical carcinoma." (PMID 27115350, 2016). "Expression of CD107a and CD161 was graphed as a percentage of gated CD4+NKG2D+ T cells in control and cervical cancer groups subdivided, in turn, into the three groups based on ranges of CD4+NKG2D+ T cell percentages, which were characterized by the expression or lack of CD28 (respectively)." (PMID 26486970, 2015).
cervical carcinoma (continued). "In this urgent study, we focused our attention on the immunophenotypic characterization of CD4+NKG2D+ T cells in patients with well-established cervical carcinoma and revealed the existence of at least two separate CD4+NKG2D+ T cell subsets defined by the co-expression or absence of CD28." (PMID 26486970, 2015). "Besides enhanced Treg-mediated immunosuppression, the profound immune dysfunction resulting from HIV-1 infection and the concomitant loss of CD4+ T cells collude to create an environment permissive for HPV persistence and cervical cancer." (PMID 24639678, 2014). "Moreover, data in the literature have shown that the clinical course of cervical cancer becomes more aggressive when the CD4+ T-cell count is low." (PMID 24760049, 2014). "CD8 and CD4 molecules dyeing from flaxen to brown were localized on membrane or in cytoplasm of lymphocytes, which distributed in stroma of epithelium and stratum basale, as well as a few expressions in cervical cancer tissues." (PMID 29147220, 2011). "In conclusion, the local expression of HLA-I, CD8 and CD4 in cervical tissue may be involved in the occurrence and progression of cervical carcinoma." (PMID 29147220, 2011). "Only 18% of HIV-positive women with cervical cancer had CD4 counts below 200 cells/μl." (PMID 20716343, 2010). "To determine the possible associations between CD4, CD8, CD25 and CD28 antigens expression in several stages of cervical cancer development, we assessed the expression of these molecules in cervical biopsies stratified according to the severity of the lesion and HPV type detected (HPV16 and 18)." (PMID 19689792, 2009). "Similarly, the proportion of CD4+ T cells was found to be significantly lower in tumors from patients (stage IA to IIA cervical carcinoma) with lymph node metastasis (n = 8) than in those from patients without lymph node metastasis (n = 22) (24.5 versus 32.7, p = 0.001)." (PMID 34553029, 2021). "Therefore, CD8+/CD4+ TIL ratio through biopsy can be a useful marker in predicting the outcome of cervical cancer and tuning the ratio of CD8+/CD4+ TILs by clinical intervention such as chemotherapy or radiotherapy may improve survival for patients." (PMID 34150643, 2021). "In conclusion, we found that 71% of participants underwent adequate cervical cancer screening and that the factors that associated with screening were parity, CD4 levels, whether or not patients had been advised about screening, and attitude toward screening." (PMID 33112557, 2020). "In addition, a study collected tumor tissue and peripheral blood samples from patients with cervical cancer and found that the CD4+ cell proportion and CD4+/CD8+ cell ratio were significantly lower in cervical cancer tissue than in the peripheral blood, which is consistent with our results." (PMID 32131750, 2020). "The associated factors related to cervical cancer screening practice were age, parity, mean age at first intercourse, CD4 level, whether or not the patient had been advised regarding cervical cancer screening, and attitude toward screening." (PMID 33112557, 2020). "CD3+ tumor infiltrating T cells (TILs), CD45RO+ TILs, CD4+ TILs, CD8+ TILs, FOXP3+ TILs (regulatory T cells, Tregs), CD68+ tumor associated macrophages (TAMs), CD163+ TAMs, and PD-L1+ tumor cells were immunostained in formalin-fixed paraffin-embedded (PPFE) tissues from 96 cervical cancer patients." (PMID 31616592, 2019). "In blood samples from patients with preinvasive and microinvasive cervical cancer tested our study, we could observe significantly higher proportion of CD4+CD95+ Т lymphocytes with a concomitant tendency for decreased percentage of CD8+CD95+ Т lymphocytes compared to healthy controls." (PMID 29075318, 2017).
cervical carcinoma (continued). "Therefore, one can expect pathological alterations that reflect the functioning of immunosuppressive mechanisms triggered by expansion of CD4 Treg population would also be detectable in the peripheral circulation during early stages of cervical cancer progression." (PMID 29075318, 2017). "With circulating CD4+NKG2D+ T cells frequently expanded in patients with cervical cancer, we wanted to explore the plasma cytokine profile, including pro- and anti-inflammatory cytokines, which may be involved in the expansion of this particular T cell population." (PMID 26486970, 2015). "Thus we speculate that CD4+CD25+CD127lo/- Treg cells may play an important role in the development of cervical cancer." (PMID 23587428, 2013). "In the general population, tumour infiltrating lymphocytes in cervical cancer have been associated with a depressed function of cytotoxic T cells; a down-regulation of CD25 (α chain of the IL-2 receptor-IL-2Rα) activated cells and a decreased proportion of CD4+ T cells with a reversed CD4/CD8 ratio." (PMID 19689792, 2009). "In our previous study using a mouse cervical cancer model, silencing PRMT5 in tumor cells not only inhibited tumor growth but also elevated both the proportion and count of CD4+ and CD8+ T cells." (PMID 41463372, 2025). "Our data shows that TF-BiTE results in a similar activation of CD4+ and CD8+ T cells, as demonstrated by a percentage increase in CD107a+ cells in cervical cancer cell lines." (PMID 41009508, 2025). "In the cervical cancer TME, CD4+ T cells are markedly reduced, while CD8+ T cell levels remain unchanged." (PMID 40539072, 2025). "The degree of CD4+ and CD8+ T cell infiltration has been shown to correlate with the severity of cervical cancer lesions." (PMID 40539072, 2025). "Persons with HIV infection, even on HAART, show an incomplete restitution of the CD4+ T cell population and, therefore, HPV persistence and early progression to cervical cancer." (PMID 40507578, 2025). "Both CD4+ and CD8+ T-cell participate in HPV-related immune response, CD8+ T-cell are considered as the primary effectors in eliminating HPV-infected and cervical cancer cells." (PMID 39252044, 2024). "However, as a cautionary note, it has been suggested that peptide-based therapeutic HPV vaccines could prove to be unsafe in-established cervical cancers since they could induce E6/E7 specific CD4 + Tregs in the environment of cancer and in the peripheral blood." (PMID 37670247, 2023). "In a word, in early cervical cancer, the proportion of CD8 + T cells was higher than that of CD4 + T cells, and it played a relatively important role." (PMID 36185274, 2022). "The cervical cancer tumor is infiltrated by tumor-infiltrating lymphocytes (TIL), meaning CD3+, CD4+, and CD8+T cells, and CD3+CD4+ (double positive) T cells are predominant in the tumor center." (PMID 36010256, 2022). "One study showed that the maturation of DCs can induce the production on CD4 +, CD8 + T cells and activated NKs, making it to become candidate target for immunotherapy of cervical cancer." (PMID 36406134, 2022). "Here, we assessed the expression of PD-1 and CD39 in circulating memory (CD45RA-) conventional (Tconv; FOXP3-) CD4 T cells from head and neck squamous cell carcinoma (HNSCC) and cervical cancer (CC) patients and from healthy donors (HDs)." (PMID 35954341, 2022). "Differences in CD4+ T cells (CD4), B cells (CD19), and NK cells (CD56) in normal samples and cervical cancer samples were detected by western blotting." (PMID 33833992, 2021). "Studies have found that in the treatment of cervical cancer, the combined use of CMNa has higher levels of CD3+, CD4+, CD4+/CD8+ (P < 0.05), and lower CD8+ levels (P < 0.05) compared with the radio-chemotherapy group alone." (PMID 33784955, 2021). "Our results indicated that increasing CD8+/CD4+ TIL ratio is a favourable prognostic factor, correlating with improved overall survival and delayed recurrence in cervical cancer." (PMID 34150643, 2021).